SETD7 (SET domain containing 7, histone lysine methyltransferase)
Description:
Histone methyltransferase that specifically monomethylates 'Lys-4' of histone H3. H3 'Lys-4' methylation represents a specific tag for epigenetic transcriptional activation. Plays a central role in the transcriptional activation of genes such as collagenase or insulin. Recruited by IPF1/PDX-1 to the insulin promoter, leading to activate transcription. Monomethylates 'Lys-189' of TAF10, leading to increase the affinity of TAF10 for RNA polymerase II. Monomethylates 'Lys-491' of CGAS, promoting interaction between SGF29 and CGAS (By similarity). Acts as a positive regulator of smoothened signaling by mediating methylation of full-length GLI3, increasing GLI3 ability to bind DNA.
Synonyms: KIAA1717; KMT7; SET7; SET9; SET7/9; LOC105377622
Tractability: Small molecule: a structure with a bound ligand is known; a high-quality ligand is known; it has a high-quality binding pocket. PROTAC: ubiquitination databases record sites on it; a small molecule that binds it is known.
Target class: Writer; Protein methyltransferase; SET domain; Epigenetic regulator
Chemical probes: (R)-PFI-2 (high quality)
Gene: Protein-coding gene on chromosome 4 (139,492,974 to 139,606,699, reverse strand). Ensembl gene ENSG00000145391.
Subcellular location: Nucleus; Chromosome
Subcellular location (Human Protein Atlas): Nucleoli; Nucleoli rim; Mitotic chromosome
Pathways (Reactome):
Chromatin organization: PKMTs methylate histone lysines
Gene Ontology:
Molecular function: histone H3 methyltransferase activity; histone H3K4 monomethyltransferase activity; histone methyltransferase activity; protein binding; protein-lysine N-methyltransferase activity
Biological process: DNA damage response; heterochromatin organization; peptidyl-lysine dimethylation; peptidyl-lysine monomethylation; positive regulation of smoothened signaling pathway; chromatin organization; positive regulation of DNA-templated transcription; chromatin remodeling; regulation of DNA repair; regulation of DNA-templated transcription
Cellular component: chromosome; nucleolus; nucleoplasm; nucleus
Genetic constraint (gnomAD): Loss-of-function variants: 12 observed, 32.11 expected, observed/expected ratio (o/e) 0.37, 90% interval 0.24 to 0.61. The upper end of that interval is the gene's LOEUF score, 0.61, which puts it in group 2 of 6, group 1 being the genes least tolerant of losing a copy. Missense variants: 289 observed, 403 expected, observed/expected ratio (o/e) 0.72, 90% interval 0.65 to 0.79. Synonymous variants: 139 observed, 149.98 expected, observed/expected ratio (o/e) 0.93, 90% interval 0.81 to 1.07.
Homologues: Orthologues: chimpanzee SETD7 (100% identical), dog SETD7 (99% identical), pig SETD7 (98% identical), rabbit SETD7 (98% identical), mouse Setd7 (95% identical), rat Setd7 (93% identical), guinea pig SETD7 (92% identical), macaque SETD7 (87% identical), tropical clawed frog setd7 (81% identical), zebrafish setd7 (73% identical). Paralogues in human: RSPH10B (17% identical), RSPH10B2 (17% identical), MORN1 (16% identical), RSPH1 (16% identical), ALS2CL (15% identical), MORN3 (11% identical), MORN2 (9% identical).
Diseases named in the same sentence as SETD7 in open-access papers:
SETD7 is named in the same sentence as 89 diseases in open-access papers, as found by Europe PMC text mining. Sharing a sentence is not in itself a finding about the gene and the disease. The quoted sentences say what the papers report.
breast cancer (34 papers, 2012 to 2024). A primary or metastatic malignant neoplasm involving the breast. "In breast cancer cells, SETD7 inhibition was associated with a less differentiated, predominantly luminal phenotype by controlling the stability of E2F1 and DNMT1." (PMID 30013796, 2018). "In addition, we found that high mRNA levels of SETD4 (p=0.0468, HR=1.92), SETD5 (p=0.00231, HR=2.79), or SETD7 (p=0.0391, HR=1.97) were significantly associated (p<0.05) with shorter survival in breast cancer patients." (PMID 25537518, 2015). "Previous studies reported that Setd7 promotes multiple malignant processes in breast cancer development." (PMID 39522095, 2024). "According to some research, SETD7 functions as a tumor suppressor in breast cancer, renal cell carcinoma, colorectal cancer, and gastric cancer." (PMID 39725038, 2024). "In breast cancer, a negative regulatory loop involving SETD7 and DNA methyltransferase 1 (DNMT1) has been observed." (PMID 38036730, 2023). "SETD7 is a breast cancer prognostic marker and a new antioxidant promoter in the face of oxidative stress." (PMID 37602329, 2023). "In breast cancer, SETD7 facilitates the transcription of vascular endothelial growth factor (VEGF), a key regulator of angiogenesis, by associating with GATA131." (PMID 38036730, 2023). "It has been reported that SETD7 methylates ERα, which plays an important role in breast cancer development and progression." (PMID 35600335, 2022). "Lung cancer, osteosarcoma, colorectal cancer and breast cancer were the most studied cancer types, where SETD7 function was reported as tumour-promoting and suppressing." (PMID 35326563, 2022). "The aim of our bioinformatic study was to assess the potential role of the protein methyltransferase SETD7 in breast cancer by using freely available resources." (PMID 36551516, 2022). "SETD7 has been reported to play a tumor-contributing role in breast cancer and hepatocellular carcinoma." (PMID 33372601, 2020). "Clinicopathologic associations of SETD7, a PKMT that mono-methylates H3K4 (H3K4me1) and activates transcription, have been reported in breast cancer and HCC." (PMID 33050946, 2020). "Upregulation of SETD7 has also been correlated with advanced nodal stage, tumor size and poor outcome in a cohort of 80 patients with all four molecular subtypes of breast cancer." (PMID 33050946, 2020). "Breast cancer patients (n=1086) were divided into two cohorts according to the median of SETD7 expression." (PMID 29212211, 2017). "Together, we proposed SETD7 as a prognostic marker of breast cancer and a novel antioxidant promoter under oxidative stress in breast cancer." (PMID 29212211, 2017). "To gain insight into the biological effect of SETD7 on breast cancer cells, we stably knocked down SETD7 expression in two parent breast cancer cell lines MCF7 and MDA-MB-231." (PMID 29212211, 2017). "In order to assess the function of SETD7 in breast cancer patients, we firstly analyzed the SETD7 expression data obtained from TCGA database." (PMID 29212211, 2017). "Using univariate and multivariate survival analysis, we determined SETD7 to be a possible prognostic marker of breast cancer." (PMID 29212211, 2017). "To investigate the clinical relevance of SETD7 in breast cancer patients, we compared the distributions of differential clinicopathological characteristics based on SETD7 expression." (PMID 29212211, 2017). "In this study, using The Cancer Genome Atlas (TCGA) database, we revealed that SETD7 was a potential prognostic marker of breast cancer." (PMID 29212211, 2017). "Here in this study, we explored the data of breast cancer from TCGA database and we demonstrated the relationship between SETD7 and poor outcome of breast cancer patients." (PMID 29212211, 2017). "To investigate the molecular mechanism of SETD7 inducing poor outcome of breast cancer patients, we explored the expression data of breast cancer in TCGA database." (PMID 29212211, 2017).
breast cancer (continued). "In conclusion, we demonstrated that SETD7 was a predictor of breast cancer prognosis and that SETD7 activated the antioxidant pathway and promoted the expression of antioxidant enzymes." (PMID 29212211, 2017). "In our study, we proposed that SETD7 acts as an activator of antioxidant pathway under stressed conditions in breast cancer." (PMID 29212211, 2017). "However, the predictive relevance of SETD7 in breast cancer and its ability to modulate intrinsic redox homeostasis has never been studied." (PMID 37602329, 2023). "Furthermore, SETD7 suppressed the proliferation, migration, and invasion of breast cancer cells through regulation of Gli-1 expression." (PMID 38036730, 2023). "The present study provides some evidence that SETD7 is an oncogene in breast cancer." (PMID 35600335, 2022). "SETD7 is a lysine N-methyltransferase that targets many proteins important in breast cancer (BC)." (PMID 36551516, 2022). "Additionally, we identified the significantly overrepresented biological processes and pathways among the differentially expressed genes that emerge when SETD7 expression is used to stratify the samples in each breast cancer subtype." (PMID 36551516, 2022). "Therefore, the authors concluded that SETD7 is a prognostic marker in breast cancer patients and an upstream transcriptional regulator of antioxidant proteins in breast cancer cells dependent on the KEAP1-NRF2 pathway." (PMID 33805996, 2021). "While further investigation of the role of SETD7 in breast cancer is warranted, these findings demonstrate that SETD7 could be a potential therapeutic target in breast cancer." (PMID 33050946, 2020). "Another example is the SETD7 potential for breast cancer treatment." (PMID 30013796, 2018). "In our study, we have proved that SETD7 could augment cell growth rate and induce anti-apoptotic effect in breast cancer." (PMID 29212211, 2017). "Combined with the result of luciferase reporter assay, we concluded that SETD7 was a potential promoter of the antioxidant pathway counterbalancing the cytotoxic effect of oxidative stress, thereby inducing the poor prognosis of breast cancer." (PMID 29212211, 2017). "Thus, depicting the role of SETD7 inducing expression of antioxidants will deepen our understanding of breast cancer progression." (PMID 29212211, 2017). "Moreover, SETD7 expression, together with the expression of downstream antioxidants, served as a good predictor of breast cancer prognosis." (PMID 29212211, 2017). "Deciphering the mechanism of SETD7 in ROS detoxification might help exploit the potential of SETD7 as a therapeutic target for breast cancer." (PMID 29212211, 2017). "Increased apoptotic effect was detected in SETD7-silenced breast cancer cells." (PMID 29212211, 2017). "Inhibiting SETD7 expression may be a good strategy for breast cancer treatment." (PMID 35600335, 2022). "Regarding ERα-positive breast cancer, SETD7 enhances the transcriptional activity of ERα; therefore, SETD7 inhibitors could also synergize with endocrine therapy, and their applicability for treating ERα-positive/endocrine-resistant breast cancer should be investigated." (PMID 30013796, 2018). "In SETD7-deficient mice, TGF-β-induced lung fibrosis is highly ameliorated, which indicates SETD7 is a positive regulator in TGF-β signaling, even plays an oncogenic role in TGF-β-mediated cancers, such as breast cancer and glioblastoma." (PMID 35812730, 2022). "Here, SETD7-mediated methylation of K302 on ER ensures protein stability and promotes DNA binding activity and the expression of ER-downstream genes, such as PS2 and progesterone receptor (PgR), in breast cancer." (PMID 35812730, 2022). "Interestingly, other study showed a negative correlation between E2F1 and SETD7 in vivo and in clinical specimens: Overexpression of E2F1 leads to SETD7 downregulation and EGFR and Snail upregulation in breast cancer cells." (PMID 35812730, 2022).
breast cancer (continued). "(R)-PFI-2 showed its activity in breast cancer cell MCF7 and mouse embryonic fibroblast in YAP-related studies and thus might be a potential therapeutic option for SETD7-mediated disease progression." (PMID 35812730, 2022). "Additionally, to evaluate the interaction effect between SETD7 and NRF2 target genes on breast cancer survival, we correlated their expression levels with patient outcome." (PMID 29212211, 2017). "Despite the regulating role of SETD7 on non-histone proteins, the function of SETD7 regulating redox state has never been intensively investigated in breast cancer." (PMID 29212211, 2017). "However, the prognostic value of SETD7 on breast cancer and the ability of SETD7 of regulating intrinsic redox homeostasis has never been investigated." (PMID 29212211, 2017).
bladder cancer (17 papers, 2017 to 2024). "In bladder cancer, the m6A modification of SETD7 mRNA by METTL3 leads to mRNA decay, which facilitates cell proliferation and metastasis." (PMID 38036730, 2023). "Recently, studies have reported that METTL3 is highly expressed in bladder cancer and degrades SETD7 and KLF4 mRNAs combined with the m6A reader YTHDF2." (PMID 37259333, 2023). "Recent studies showed that METTL3-mediated m6A hypermethylation promotes the progression of bladder cancer by regulating SETD7/KLF4 mRNA expression, pri-mrR221/222 maturation and AFE4/NF-κB/MYC signaling network activation." (PMID 35945641, 2022). "M6A readers (YTHDF2, IGF2BP1, and IGF2BP3) promote the progression of bladder cancer by stabilizing SETD7, KLF4, FSCN1, and MYC mRNA and regulating JAK/STAT signaling pathway activation." (PMID 35945641, 2022). "SETD7 also exhibits tumor-suppressive effects in lung and bladder cancer." (PMID 38036730, 2023). "In bladder cancer, the mutual interaction between METTL3 and YTHDF2 induced the degradation of SETD7 and KLF4 mRNA in the proliferation and metastasis process." (PMID 34996459, 2022). "YTHDF2 promotes the mRNA degradation of tumor suppressor genes SET domain containing lysine methyltransferase 7 (SETD7) and Kruppel Like Factor 4 (KLF4) by identifying METTL3-mediated m6A modification, thus inducing bladder cancer progression." (PMID 33692959, 2021). "Luckily, it was found that YTHDF2 was up-regulated in bladder cancer and the up-regulated YTHDF2 advanced the progression of bladder cancer through cooperating with METTL3 and directly degrading the mRNAs of SETD7 and KLF4 in an m6A dependent manner." (PMID 33593354, 2021). "YTHDF2 recognizes these m6A modifications and degrades the SETD7 and KLF4 mRNAs, leading to bladder cancer progression." (PMID 32765970, 2020). "Similarly, in our previous study, we also found that the expression of METTL3 and YTHDF2 was up‐regulated in bladder cancer and showed that METTL3 inhibited the expression of SETD7 and KLF4 in an m6A‐YTHDF2‐dependent manner to further promote the proliferation and metastasis of bladder cancer." (PMID 32808488, 2020).
prostate carcinoma (17 papers, 2016 to 2024). A carcinoma that arises from epithelial cells of the prostate gland. "SETD7 with frameshift mutation in castration-resistant prostate cancer is the downstream target of miR-153; overexpression of miR-153 also promotes degradation of SETD7 and then suppresses ovarian cancer cell proliferation and invasion." (PMID 27183310, 2016). "Interestingly, a whole transcriptomic sequencing of eight castration-resistant prostate cancer samples revealed a frameshift mutation of SETD7 in one of them." (PMID 35326563, 2022). "This study identified a novel locus associated with serum lycopene concentrations and our results raise a number of intriguing possibilities regarding the nature of the relationship between SETD7 and lycopene, both of which have been independently associated with prostate cancer." (PMID 26861389, 2016). "It is also plausible that SETD7 may be related to prostate cancer risk through its relationship to serum lycopene concentrations, as was identified in this study." (PMID 26861389, 2016). "Our previous study, we observed that Setd7 knockdown decreased colony formation in human prostate cancer PC-3 and LNCaP cells." (PMID 39522095, 2024). "In a previous study, we observed that Setd7 knockdown decreased colony formation in human prostate cancer PC-3 and LNCaP cells." (PMID 39522095, 2024). "In this regard, SET domain-containing lysine methyltransferase 7 (Setd7) represents an epigenetic regulator of Nrf2 pathway in prostate cancer cells." (PMID 35158943, 2022). "It would be interesting to explore the influence of SETD7 over NFκB and ERα, as well as AR transrepression and positive cross-talk as these pathways play key roles in breast and prostate cancer." (PMID 30013796, 2018). "SETD7 is proliferative and anti-apoptotic in prostate cancer cells and nuclear expression is upregulated in prostate cancer tissue." (PMID 26861389, 2016). "Our results raise a number of intriguing possibilities regarding the nature of the relationships previously noted between SETD7, lycopene, and prostate cancer." (PMID 26861389, 2016). "However, others have noted an oncogenic role for SETD7 in prostate cancer, hepatocellular carcinoma, and intestinal tumorigenesis." (PMID 39725038, 2024). "In our previous study, we observed that Setd7 knockdown decreased the colony formation in human prostate cancer PC-3 and LNCaP cells, and Ingenuity® Pathway Analysis of microarray data showed Setd7 KD attenuates cell growth/proliferative pathways and activates the cell apoptosis pathways." (PMID 39522095, 2024). "In, line with this, SETD7 methylation of estrogen and androgen receptor enhances their transcriptional activity, so future studies to identify its function in breast and prostate cancer could provide novel insights to treat endocrine-resistant cases." (PMID 35326563, 2022). "The activity of SETD7 as a histone methyltransferase (HMT) may also play a role in prostate cancer." (PMID 26861389, 2016).
Hyperglycemia (14 papers, 2015 to 2024). An increased concentration of glucose in the blood. "SETD7 has been previously implicated in hyperglycemia-induced epigenetic activation of profibrotic genes related to nephropathies and vascular complications (TGFβ, SERPINE1, COL1A, and MCP-1), being involved in metabolic memory." (PMID 28545403, 2017).
renal fibrosis (13 papers, 2016 to 2025). A final common manifestation of a wide variety of chronic kidney diseases characterized by glomerulosclerosis and tubulointerstitial fibrosis. "SETD7 mediates M2 macrophages-myofibroblasts transition, bone marrow-derived myofibroblasts activation, and inflammation response in the development of renal fibrosis." (PMID 35559246, 2022). "A recent study also reported that SETD7 expression is associated with the degree of fibrosis in patients with IgA and membranous nephropathy and inhibition of SETD7 suppressed renal fibrosis in unilateral ureteral obstruction mice." (PMID 27736906, 2016). "In UUO mice, inhibition of SETD7 expression can reduce renal fibrosis." (PMID 35559246, 2022). "Inhibition of SETD7 suppresses MMT and myeloid-derived myofibroblast aggregation, reduces the inflammatory response, and inhibits the progression of renal fibrosis." (PMID 39445007, 2024). "Inhibition of SETD7 inhibits the aggregation of M2MMT and bone marrow-derived myofibroblasts, attenuates the inflammatory response, and inhibits the development of renal fibrosis." (PMID 39445007, 2024). "The remaining signalling pathways mediating renal fibrosis are STING/TBK1, IL-4Ra/STAT6, Jmjd3/IRF4, STAT6/PPARα, SETD7, NKT/IL-4, BRP-39, STAT-1/TREM-1, MMP-9/Akt, adiponectin/APK, and JAK3/STAT6." (PMID 39445007, 2024). "It is also reported that the methyltransferase SET9 (also known as SETD7) can interact with the Smad3 N-terminal MH1 domain to increase Smad3 activity and upregulate α-SMA expression during renal fibrosis." (PMID 35541902, 2022). "In addition, previous studies have shown that SETD7 contributes to AKI and renal fibrosis in diabetic mice." (PMID 35559246, 2022).